GORASP1 (golgi reassembly stacking protein 1)
Description:
Key structural protein of the Golgi apparatus. The membrane cisternae of the Golgi apparatus adhere to each other to form stacks, which are aligned side by side to form the Golgi ribbon. Acting in concert with GORASP2/GRASP55, is required for the formation and maintenance of the Golgi ribbon, and may be dispensable for the formation of stacks. However, other studies suggest that GORASP1 plays an important role in assembly and membrane stacking of the cisternae, and in the reassembly of Golgi stacks after breakdown during mitosis (By similarity). Caspase-mediated cleavage of GORASP1 is required for fragmentation of the Golgi during apoptosis (By similarity). Also mediates, via its interaction with GOLGA2/GM130, the docking of transport vesicles with the Golgi membranes. Mediates ER stress-induced unconventional (ER/Golgi-independent) trafficking of core-glycosylated CFTR to cell membrane.
Synonyms: GOLPH5; GRASP65; P65; FLJ23443
Tractability: Antibody: UniProt places it where antibodies can reach, with high confidence. PROTAC: ubiquitination databases record sites on it; its protein half-life has been measured.
Gene: Protein-coding gene on chromosome 3 (39,095,222 to 39,108,369, reverse strand). Ensembl gene ENSG00000114745.
Subcellular location: Golgi apparatus, cis-Golgi network membrane; Endoplasmic reticulum- Golgi intermediate compartment membrane
Subcellular location (Human Protein Atlas): Golgi apparatus
Pathways (Reactome):
Vesicle-mediated transport: COPI-mediated anterograde transport; COPII-mediated vesicle transport
Cell Cycle: Golgi Cisternae Pericentriolar Stack Reorganization
Gene Ontology:
Molecular function: protein binding
Biological process: establishment of protein localization to plasma membrane; Golgi ribbon formation; negative regulation of dendrite morphogenesis; Golgi organization
Cellular component: endoplasmic reticulum-Golgi intermediate compartment membrane; Golgi apparatus; cis-Golgi network; Golgi membrane
Genetic constraint (gnomAD): Loss-of-function variants: 33 observed, 41.31 expected, observed/expected ratio (o/e) 0.8, 90% interval 0.6 to 1.07. The upper end of that interval is the gene's LOEUF score, 1.07, which puts it in group 4 of 6, group 1 being the genes least tolerant of losing a copy. Missense variants: 476 observed, 574.33 expected, observed/expected ratio (o/e) 0.83, 90% interval 0.77 to 0.89. Synonymous variants: 204 observed, 229.12 expected, observed/expected ratio (o/e) 0.89, 90% interval 0.79 to 1.
Homologues: Orthologues: chimpanzee GORASP1 (100% identical), macaque GORASP1 (93% identical), mouse Gorasp1 (83% identical), rabbit GORASP1 (82% identical), rat Gorasp1 (81% identical), pig GORASP1 (80% identical), guinea pig GORASP1 (78% identical), zebrafish gorasp1a (47% identical), tropical clawed frog gorasp1 (47% identical), zebrafish gorasp1b (36% identical), Caenorhabditis elegans Y42H9AR.1 (33% identical), Drosophila melanogaster Grasp65 (32% identical). Paralogues in human: GORASP2 (40% identical).
Diseases named in the same sentence as GORASP1 in open-access papers:
GORASP1 is named in the same sentence as 21 diseases in open-access papers, as found by Europe PMC text mining. Sharing a sentence is not in itself a finding about the gene and the disease. The quoted sentences say what the papers report.
cancer (6 papers, 2014 to 2025). A tumor composed of atypical neoplastic, often pleomorphic cells that invade other tissues. "Proteins encoded by a part of these genes are involved in signaling pathways and biological processes frequently affected in cancer, like apoptosis (GORASP1), regulation of actin cytoskeleton (FGD5), transmembrane signaling systems (GNAI2) or regulation of NFkappaB activity (NKIRAS1)." (PMID 28326264, 2015). "Identified genes included well-known TSGs VHL, CTDSPL, LRRC3B, ALDH1L1, and EPHB1, but also genes not previously linked to cancer development (LRRN1, GORASP1, FGD5, and PLCL2)." (PMID 28326264, 2015). "These genes include tumor suppressors or candidates (VHL, CTDSPL, LRRC3B, ALDH1L1, and EPHB1) and genes that were not previously considered as cancer-associated (e.g., LRRN1, GORASP1, FGD5, and PLCL2)." (PMID 24977159, 2014). "But there are also a number of genes which have not been previously reported as involved in cancer development, such as LRRN1, GORASP1, FGD5, and PLCL2." (PMID 24977159, 2014).
neurodevelopmental disorder (1 paper, 2025). A behavioral and cognitive disorder with onset during the developmental period that involves impaired or aberrant development of intellectual, motor, or social functions. "Herein, we report the identification of the first human GORASP1 variant in a male patient with a neurodevelopmental disorder associating neurosensory, neuromuscular, and skeletal abnormalities." (PMID 39933924, 2025). "Here, we report the identification of the first human pathogenic variant of GORASP1 (c.1170_1171del; p.Asp390Glufs*18) in a patient combining a neurodevelopmental disorder with neurosensory, neuromuscular, and skeletal abnormalities." (PMID 39933924, 2025). "However, as several other Golgi proteins are associated with neurodevelopmental disorders with symptoms that are similar to our patient’s phenotype, we considered the GORASP1 variant as a relevant causal candidate for the patient’s disease." (PMID 39933924, 2025).
GORASP1 also shares sentences with these, for which no sentence is quoted: tumor (4 papers); Alzheimer disease (3); infection (3); colon carcinoma (2); cytomegalovirus infection (2); ovarian carcinoma (2); acute pancreatitis (1); breast carcinoma (1); Legionella infection (1); leukemia (1); Lewis lung carcinoma (1); lung carcinoma (1); melanoma (1); Muscular dystrophies (1); myopia (1); prostate carcinoma (1); small cell lung carcinoma (1); Truncal obesity (1); vitreoretinal degeneration (1).